OR9Q2 (olfactory receptor family 9 subfamily Q member 2)
Description:
Odorant receptor.
Synonyms: OR9Q2P
Tractability: Antibody: UniProt places it where antibodies can reach, with medium confidence; UniProt predicts a signal peptide or a membrane-spanning region; its Gene Ontology location is reachable by antibodies, with medium confidence.
Gene: Protein-coding gene on chromosome 11 (58,189,070 to 58,194,053, forward strand). Ensembl gene ENSG00000186513.
Subcellular location: Cell membrane
Pathways (Reactome):
Sensory Perception: Expression and translocation of olfactory receptors
Gene Ontology:
Molecular function: olfactory receptor activity; G protein-coupled receptor activity
Biological process: G protein-coupled receptor signaling pathway; sensory perception of smell; detection of chemical stimulus involved in sensory perception of smell
Cellular component: plasma membrane; membrane
Genetic constraint (gnomAD): Loss-of-function variants: 14 observed, 13.06 expected, observed/expected ratio (o/e) 1.07, 90% interval 0.71 to 1.65. The upper end of that interval is the gene's LOEUF score, 1.65, which puts it in group 6 of 6, group 1 being the genes least tolerant of losing a copy. Missense variants: 398 observed, 416.61 expected, observed/expected ratio (o/e) 0.96, 90% interval 0.88 to 1.04. Synonymous variants: 176 observed, 167.86 expected, observed/expected ratio (o/e) 1.05, 90% interval 0.93 to 1.19.
Homologues: Orthologues: chimpanzee OR9Q2 (98% identical), mouse Or9q2 (86% identical), macaque OR9Q2 (85% identical), pig OR9Q2 (84% identical), rat Or9q2 (83% identical), rabbit OR9Q2 (83% identical), guinea pig OR9Q2 (82% identical). Paralogues in human: OR9Q1 (72% identical), OR9I1 (61% identical), OR5B21 (54% identical), OR5B12 (51% identical), OR5A1 (50% identical), OR5AP2 (49% identical), OR5C1 (49% identical), OR8U3 (49% identical), OR5AR1 (49% identical), OR5B3 (49% identical), OR8U1 (48% identical), OR9H1 (48% identical), and 84 more.
Diseases named in the same sentence as OR9Q2 in open-access papers:
OR9Q2 is named in the same sentence as 1 disease in open-access papers, as found by Europe PMC text mining. Sharing a sentence is not in itself a finding about the gene and the disease.
OR9Q2 shares sentences with these, for which no sentence is quoted: breast carcinoma (1 paper).